ALDH5A1 (aldehyde dehydrogenase 5 family member A1)
Diseases named in the same sentence as ALDH5A1 in open-access papers (continued):
Sharing a sentence is not in itself a finding about the gene and the disease.
nephropathic cystinosis (1 paper, 2006). An autosomal recessive condition caused by mutation(s) in the CTNS gene, encoding cystinosin. "For example, SIV-infected genome contains upregulated aldehyde dehydrogenase 5 family member A1 (ALDH5A1, ID: H06676); and concurrent down regulated succinate dehydrogenase complex, subunit D (SDHD, ID: AA035384) and nephropathic cystinosis (CTNS, ID: W94331)." (PMID 16956415, 2006).
neutropenia (1 paper, 2024). A decrease in the number of neutrophils found in the blood. "In our group of patients, the presence of ALDH5A1 rs1054899 genotype AC increased the risk of early and recurrent severe neutropenia." (PMID 39596349, 2024). "In our study, the risk of severe recurrent neutropenia (grades 3 and 4) was independently influenced by the ABCB1 rs17064 genotype AT (OR 5.13; 1.38–19.02; p = 0.014), UGT2B4 rs1131878 genotype AG (OR 3.78; 1.26–11.24; p = 0.016), and ALDH5A1 genotype AC (OR 3.94; 1.34–11.53; p = 0.012)." (PMID 39596349, 2024).
opioid dependence (1 paper, 2021). "Interestingly, variants of ALDH5A1 have been shown to influence patient responses to methadone treatment, the predominant therapy for opioid dependence." (PMID 34203972, 2021).
pancreatic adenocarcinoma (1 paper, 2025). "Next, the expression of ALDH1L1, ALDH3A1, ALDH3B1, and ALDH5A1 in pancreatic adenocarcinoma (PAAD) samples was compared with that of matching TCGA and GTEx normal samples using GEPIA2." (PMID 40868269, 2025).
pancreatic cancer (1 paper, 2025). "High expression of ALDH1L1, ALDH3A1, and ALDH3B1 was associated with shorter overall survival, while ALDH5A1 expression was associated with longer overall survival of pancreatic cancer patients." (PMID 40868269, 2025). "In this study comprehensively analyzed ALDHs in PAAD and identified four genes (ALDH1L1, ALDH3A1, ALDH3B1, ALDH5A1) as prognostic indicators for pancreatic cancer." (PMID 40868269, 2025). "ALDH1L1, ALDH3A1, ALDH3B1, and ALDH5A1 may serve as potential prognostic markers and predictors of chemotherapy response in pancreatic cancer patients." (PMID 40868269, 2025).
thyroid cancer (1 paper, 2023). "Mechanically, ALDH5A1 can enhance the migration and invasion ability of thyroid cancer cells through EMT transition, suggesting that ALDH5A1 may emerge as a new target for PTC therapy." (PMID 36694633, 2023).
metabolic disorder (9 papers, 2015 to 2025). "Patients with metabolic disorder-related genes (ALDH5A1 and MMUT) are known to develop neurological disorders; however, seizures are not always the first or the most remarkable symptom requiring medication." (PMID 34992632, 2021).
tumor (8 papers, 2008 to 2025). "TFRC and ALDH5A1 were located in the tumour, PDLIM3 in the stroma, and CA1 and APM2 in both regions." (PMID 40697100, 2025). "It was found that in all three datasets, ALDH5A1 mRNA expression decreased with an increase in tumor grade, grade IV having the lowest expression." (PMID 39039535, 2024). "Overall, our findings suggest that miR-210 mediated downregulation of ALDH5A1 plays a critical role in tumor metabolism and helps maintaining a high glycolytic phenotype in GBM." (PMID 39039535, 2024). "Specifically, in the staining images of the tumour and stroma regions, ALDH5A1, TFRC, and PDLIM3 showed different staining intensities between the two regions, whereas APM2 exhibited poor recognition in differentiating tumour from stroma." (PMID 40697100, 2025). "Overall, our study shows for the first time that miR-210 mediated targeting of the mitochondrial ALDH5A1 reprograms the metabolism of GBM cells and also uncovers the tumor suppressive role of ALDH5A1 in GBM." (PMID 39039535, 2024). "Furthermore, we show that ALDH5A1 is downregulated in GBM patients, acts as a tumor suppressor in cell lines, and its high expression correlates with improved patient survival, further strengthening its clinical significance." (PMID 39039535, 2024). "The study suggested that ALDH5A1 was involved in the degradation of GABA via transmission across the chemical synapses pathway to produce high concentrations of succinic acid, which was broadly known to be helpful for tumor growth and metastasis." (PMID 39252305, 2024). "ALDH5A1 mRNA levels were found to be significantly downregulated in the GBM tissues of the TCGA GBM, Rembrandt, and Gravendeel datasets as compared to the non-tumor samples." (PMID 39039535, 2024). "Results showed that LMDs have high ABAT and ALDH5A1 expression, indicating that ABAT may serve a vital role for metastatic tumor cells in the CSF." (PMID 34192534, 2021). "Moreover, ALDH5A1 overexpression decreased cellular proliferation, 3D-spheroid forming ability, and the formation of reactive oxygen species (ROS) of GBM cells, suggesting its tumor suppressive role." (PMID 39039535, 2024). "For ALDH5A1 and APM2, although their MS signals were attenuated in CP‐s both tumour and stroma, their IHC signals were not significantly different between CP‐i and CP‐s, regardless of tumour or stroma." (PMID 40697100, 2025). "Further examination of the IHC signals in the tumour and stroma between CP‐i and CP‐s revealed that TFRC and PDLIM3 displayed significantly increased abundance in CP‐s, but not in CP‐i, and ALDH5A1 and APM showed no significant changes between CP‐i and CP‐s." (PMID 40697100, 2025). "TaqmanTM qRT-PCR studies of UM-C6 tumor cells verified that ALDH1A1 gene expression was reduced 88% versus Luciferase-targeted shRNA transduced control cells, whereas neither ALDH3A1 nor ALDH5A1 gene expression were altered." (PMID 18560594, 2008).
cancer (6 papers, 2012 to 2025). A tumor composed of atypical neoplastic, often pleomorphic cells that invade other tissues. "Since cellular proliferation is directly linked with the metabolism of cancer cells, we mainly studied the role of ALDH5A1 in regulating the proliferative capaity of GBM cells." (PMID 39039535, 2024). "Based on the existing evidences in other cancers, we were interested in exploring the ALDH5A1/miR-210 axis in GBM, possibly uncovering its role in altered metabolism." (PMID 39039535, 2024). "As reports on the role on ALDH5A1 in cancer metabolism are scarce, we were interested to study its functional role in GBM metabolism." (PMID 39039535, 2024). "Not surprisingly, several ALDH isoforms other than ALDH1A1 have been proved being associated with certain cancers, e.g., ALDH3A1 in lung cancer and prostate cancer and ALDH5A1 in breast cancer." (PMID 30220009, 2019). "It is noteworthy that some isoforms, such as ALDH2, ALDH3A2, ALDH3B1, and ALDH5A1, are expressed at similar levels across cancer types." (PMID 30220009, 2019). "Thus, dysregulation of ALDH5A1 levels would most likely alter cancer cell metabolism, by disturbing the balance between the major metabolic pathways- oxidative phosphorylation and aerobic glycolysis." (PMID 39039535, 2024). "ALDH1A2 is expressed at very low level in all types of cancer, whereas ALDH1B1, ALDH3B1, and ALDH5A1 are expressed at medium level universally, implying a ubiquitous role of these isoforms." (PMID 30220009, 2019). "The low levels of ALDH5A1 in GBM might be partially due to its targeting by miR-210, which is highly expressed in this cancer." (PMID 39039535, 2024). "Of the 371 cancer-related genes detected in the TCGA dataset, 190 were significantly correlated with ALDH5A1 (130 positive/60 negative) and 178 with AKR7A2 (23 positive/155 negative)." (PMID 28032215, 2017). "However, no cancer-type specific expression preference of ALDH1A2, ALDH1B1, ALDH3B1, and ALDH5A1 has been observed." (PMID 30220009, 2019).
heart (1 paper, 2021). "The metabolic network of butanoate metabolism involved ALDH5A1 and EHHADH, which could contribute to myocardial tissue damage in cyanotic congenital heart of ToF." (PMID 35174118, 2021).
hematological disease (1 paper, 2022). "In addition, genes associated with hematological disease (e.g., PDE7A, LMAN1, F13A1, OLR1) and mitochondrial biogenesis and redox (e.g., NOS3, ALDH5A1, PRXL2A, SLC25A13, CPT2) were also significantly altered in BPD patients." (PMID 35484630, 2022).
movement disorder (1 paper, 2021). Neurological conditions resulting in abnormal voluntary or involuntary movement, which may impact the speed, fluency, quality and ease of movement. "Finally, impaired neurotransmission due to the defect of dopamine and GABA metabolism (PARKIN, GCH and ALDH5A1 mutations) is responsible for exercise- induced movement disorders." (PMID 34140924, 2021).
ALDH5A1 also shares sentences with these, for which no sentence is quoted: neurological disorders (6 papers); Cognitive impairment (3); Intellectual disability (3); autosomal recessively inherited disorder (2); genetic disease (2); infection (2); Rett syndrome (2); absence seizures (1); age-related macular degeneration (1); alcohol addiction (1); Alzheimer disease (1); Anxiety (1); autism (1); autistic spectrum disorder (1); breast ductal carcinoma (1); Childhood onset (1); choroideremia (1); ciliopathies (1); cystadenoma (1); depression (1); diabetic neuropathy (1); Failure to thrive (1); female infertility (1); galactosemia (1); Guillain-Barre syndrome (1); hepatocellular carcinoma (1); Hyperammonemia (1); hyperprolinemia (1); hyperprolinemia type 2 (1); Hypertension (1).
A further 24 diseases each share a sentence with ALDH5A1 in 1 paper.